YAE1 (YAE1 maturation factor of ABCE1)
Description:
The complex LTO1:YAE1 functions as a target specific adapter that probably recruits apo-ABCE1 to the cytosolic iron-sulfur protein assembly (CIA) complex machinery. May be required for biogenesis of the large ribosomal subunit and initiation of translation.
Synonyms: C7orf36; YAE1D1; GK003; CIAB2
Tractability: PROTAC: ubiquitination databases record sites on it.
Gene: Protein-coding gene on chromosome 7 (39,566,379 to 39,612,089, forward strand). Ensembl gene ENSG00000241127.
Subcellular location: Cytoplasm; Nucleus
Subcellular location (Human Protein Atlas): Cytosol
Gene Ontology:
Molecular function: protein binding
Biological process: protein maturation
Cellular component: cytoplasm; nucleus
Genetic constraint (gnomAD): Loss-of-function variants: 24 observed, 26.66 expected, observed/expected ratio (o/e) 0.9, 90% interval 0.65 to 1.27. The upper end of that interval is the gene's LOEUF score, 1.27, which puts it in group 5 of 6, group 1 being the genes least tolerant of losing a copy. Missense variants: 260 observed, 277.07 expected, observed/expected ratio (o/e) 0.94, 90% interval 0.85 to 1.04. Synonymous variants: 101 observed, 103.37 expected, observed/expected ratio (o/e) 0.98, 90% interval 0.83 to 1.15.
Homologues: Orthologues: chimpanzee YAE1 (99% identical), macaque YAE1 (96% identical), dog YAE1 (84% identical), rabbit YAE1 (81% identical), guinea pig YAE1 (80% identical), pig YAE1 (74% identical), rat Yae1 (72% identical), rat Yae1l1 (71% identical), mouse Yae1d1 (67% identical), zebrafish otulina (27% identical).
Diseases named in the same sentence as YAE1 in open-access papers:
YAE1 is named in the same sentence as 3 diseases in open-access papers, as found by Europe PMC text mining. Sharing a sentence is not in itself a finding about the gene and the disease. The quoted sentences say what the papers report.
tumor (1 paper, 2025). "When comparing tumor tissues to standard controls, a substantial upregulation of four genes was observed: CENPQ, YAE1, FANCF, and POC5." (PMID 41502527, 2025).
YAE1 also shares sentences with these, for which no sentence is quoted: cancer (1 paper); melanoma (1).